GGT5 (gamma-glutamyltransferase 5)
Description:
Cleaves the gamma-glutamyl bond of extracellular glutathione tripeptide (gamma-Glu-Cys-Gly) and certain glutathione conjugates. Hydrolyzes glutathione releasing L-Glu and Cys-Gly dipeptide which is further metabolized to maintain extracellular cysteine levels but also to provide cysteine necessary for intracellular glutathione synthesis. Among glutathione-S-conjugates metabolizes leukotriene C4 (LTC4) and S-geranylgeranyl-glutathione (GGG), but is inactive toward gamma-glutamyl leucine. Converts extracellular LTC4 to LTD4 during acute inflammatory response. Acts as a negative regulator of GGG bioactivity. GGT5 (via GGG catabolism) and ABCC1 (via extracellular transport) establish GGG gradients within lymphoid tissues to position P2RY8-positive lymphocytes at germinal centers in lymphoid follicles and restrict their chemotactic transmigration from blood vessels to bone marrow parenchyma (By similarity). The transpeptidation reaction, i.e. the transfer of gamma-glutamyl moiety to an acceptor molecule to yield a new gamma-glutamyl compound requires high concentration of dipeptide acceptor and is considered nonphysiological.
Synonyms: GGT-rel; GGT 5; GGTLA1; GGL
Tractability: Antibody: its Gene Ontology location is reachable by antibodies, with high confidence; UniProt predicts a signal peptide or a membrane-spanning region.
Gene: Protein-coding gene on chromosome 22 (24,218,000 to 24,245,748, reverse strand). Ensembl gene ENSG00000099998.
Subcellular location: Membrane
Subcellular location (Human Protein Atlas): Nucleoli fibrillar center
Pathways (Reactome):
Metabolism: Aflatoxin activation and detoxification; Glutathione synthesis and recycling; Synthesis of Leukotrienes (LT) and Eoxins (EX)
Disease: LTC4-CYSLTR mediated IL4 production
Drug ADME: Paracetamol ADME
Gene Ontology:
Molecular function: glutathione hydrolase activity; leukotriene-C(4) hydrolase; peptidyltransferase activity
Biological process: amino acid metabolic process; fatty acid metabolic process; glutathione catabolic process; leukotriene D4 biosynthetic process; proteolysis; inflammatory response; glutathione metabolic process
Cellular component: plasma membrane; membrane
Genetic constraint (gnomAD): Loss-of-function variants: 48 observed, 51.18 expected, observed/expected ratio (o/e) 0.94, 90% interval 0.74 to 1.19. The upper end of that interval is the gene's LOEUF score, 1.19, which puts it in group 5 of 6, group 1 being the genes least tolerant of losing a copy. Missense variants: 783 observed, 728.99 expected, observed/expected ratio (o/e) 1.07, 90% interval 1.01 to 1.14. Synonymous variants: 364 observed, 314.04 expected, observed/expected ratio (o/e) 1.16, 90% interval 1.06 to 1.26.
Homologues: Orthologues: macaque GGT5 (96% identical), chimpanzee GGT5 (93% identical), dog GGT5 (80% identical), guinea pig GGT5 (80% identical), pig GGT5 (78% identical), mouse Ggt5 (78% identical), rat AABR07044631.2 (77% identical), rabbit GGT5 (75% identical), zebrafish ggt5a (39% identical), Caenorhabditis elegans C53D5.5 (35% identical), tropical clawed frog ggt5 (33% identical), Drosophila melanogaster Ggt-1 (32% identical), and 4 more. Paralogues in human: GGT1 (40% identical), GGT7 (28% identical), GGT6 (19% identical), GGTLC1 (15% identical), GGTLC3 (15% identical), GGTLC2 (13% identical).
Diseases named in the same sentence as GGT5 in open-access papers:
GGT5 is named in the same sentence as 46 diseases in open-access papers, as found by Europe PMC text mining. Sharing a sentence is not in itself a finding about the gene and the disease. The quoted sentences say what the papers report.
gastric cancer (9 papers, 2021 to 2025). A primary or metastatic malignant neoplasm involving the stomach. "TIDE analysis predicted that high GGT5 expression is associated with a poorer response to ICIs in gastric cancer, prompting further investigation into how GGT5 affects the TME of GC." (PMID 38748299, 2024). "GGT5 exhibits upregulation in gastric cancer, with its overexpression significantly linked to histological differentiation in GC patients (P < 0.05)." (PMID 38581025, 2024). "The dichotomized expression level of GGT5 protein (low versus high) was notably associated with histological differentiation in patients with gastric cancer (p < 0.05)." (PMID 38581025, 2024). "Multivariate analysis indicates that elevated GGT5 expression is an independent risk factor associated with poorer overall survival in gastric cancer patients (P < 0.05)." (PMID 38581025, 2024). "Because overexpression of GGT5 was highly associated with a poor prognosis in gastric cancer, we further investigated the correlation between immune cell infiltration and GGT5 expression to understand the potential mechanisms." (PMID 35368661, 2022). "Multivariate analysis suggested that high expression of GGT5 was an independent risk factor related to the worse overall survival of gastric cancer patients." (PMID 35368661, 2022). "Collectively, GGT5-high expression gastric cancers were associated with a relatively higher pathological stage (TNM stage and T stage) and histological grade." (PMID 35368661, 2022). "Recent studies revealed that high gamma-glutamyl-transferase 5 (GGT5) expression was associated with a poor prognosis of gastric cancer patients." (PMID 35368661, 2022). "Second, the association between GGT5 expression and immune cell infiltration as well as the direct molecular mechanism of GGT5 involvement in the progression of gastric cancer need further validation." (PMID 35368661, 2022). "Additionally, multivariate analysis demonstrated that GGT5 expression and tumor size were independent risk factors for gastric cancer progression (all p < 0.05)." (PMID 38581025, 2024). "Furthermore, the overexpression of GGT5 is inversely linked to the survival of gastric cancer patients." (PMID 38581025, 2024). "Furthermore, the univariate logistic regression analysis indicated that the expression level of GGT5 was closely associated with the clinical characteristics of a poor prognosis in patients with gastric cancer." (PMID 35368661, 2022). "Upregulated GGT5 was proven to be closely associated with poor overall survival and progression-free intervals in gastric cancer patients and could be applied as a clinically independent prognostic factor." (PMID 35368661, 2022). "GGT5 was associated with immune cell infiltration and might be a potential immunological therapeutic target in gastric cancer." (PMID 36147494, 2022). "Moreover, highly expressed GGT5 was proven to be closely associated with a high histological grade, pathological stage, and poor prognosis of gastric cancer patients." (PMID 35368661, 2022). "We also explored the correlation of GGT5 expression with immune-related genes and immune checkpoint genes to further understand the underlying mechanism by which GGT5 is correlated with immune cell infiltration in gastric cancer." (PMID 35368661, 2022). "GGT5 acts as a tumor suppressor in HCC but promotes progression in gastric cancer via PI3K/AKT pathway activation." (PMID 41316810, 2025). "Bioinformatic studies based on clinical gastric cancer samples from the Gene Expression Omnibus (GEO) and The Cancer Genome Atlas (TCGA) databases indicate GGT5’s inclusion in prognostic gene signatures." (PMID 38581025, 2024). "In our study, CIBERSORT analysis revealed the infiltration of 8 kinds of immune cells between different expression group of GGT5 in gastric cancer." (PMID 38748299, 2024).
gastric cancer (continued). "Utilizing data from TCGA and Oncomine databases, we scrutinized the differential expression of GGT5 mRNA between gastric cancer (GC) and normal gastric tissues." (PMID 38581025, 2024). "Our study is the first to propose that GGT5 wields a remarkable effect on the initiation and progression of gastric cancer, while concurrently regulating the immune milieu by preserving live memory CD8+ T cells." (PMID 38748299, 2024). "To further interrogate the association between GGT5 and CD8+ T cells, we obtained markers for 28 immune cell types and conducted ssGSEA analysis to explore the interplay among these immune cells, GGT5, and gastric cancer tumor stage using the TISIDB database." (PMID 38748299, 2024). "Examining mRNA levels in 15 pairs of gastric cancer and parental normal tissues from our center revealed elevated GGT5 levels in 11 cancer tissues (p < 0.05)." (PMID 38581025, 2024). "In delving into the biological function of GGT5 in gastric cancer, GSEA analysis revealed potential significant enrichment pathways in the high-expression GGT5 group, particularly implicating involvement in EMT." (PMID 38581025, 2024). "GGT5 protein levels in six gastric cancer cell lines and a normal human gastric epithelial cell line (GES-1) were assessed using WB, revealing elevated GGT5 protein levels in all gastric cancer cell lines compared to GES-1." (PMID 38581025, 2024). "IHC assays were conducted to assess GGT5 protein levels in the 90 cases of gastric cancer and their paired adjacent normal tissues." (PMID 38581025, 2024). "To better understand the correlation and potential mechanism of the expression of GGT5 in cancer, we studied the relationship between the expression of GGT5 and the clinical characteristics of gastric cancer patients in the TCGA database." (PMID 35257007, 2022). "Then we further searched for these differential genes on PubMed, and we found that GGT5 was upregulated in gastric cancer in these data sets, and few people had studied it." (PMID 35257007, 2022). "The Kaplan-Meier method, Cox regression, and univariate logistic regression were performed to investigate the relationships between GGT5 and clinical characteristics in gastric cancer patients." (PMID 35368661, 2022). "Our research confirmed the differential expression of GGT5 between gastric cancer and normal tissues and increased our understanding of GGT5 and the progression of gastric cancer from the perspective of immune cell infiltration." (PMID 35368661, 2022). "Univariate logistic regression assesses the relationships between GGT5 and clinical characteristics of gastric cancer patients." (PMID 35368661, 2022). "In the present study, we aimed to confirm the expression and prognostic value of GGT5 and its correlation with immune cell infiltration in gastric cancer." (PMID 35368661, 2022). "Our research provides a novel perspective for further understanding the mechanisms by which GGT5 is correlated with immune cell infiltration in the tumor microenvironment of gastric cancer." (PMID 35368661, 2022). "Clinical characteristics of gastric cancer patients in the GGT5-high and the GGT5-low expression groups." (PMID 35368661, 2022). "Next, we compared the expression level of GGT5 between gastric cancer tissues and adjacent normal tissues using the TCGA database and further validated it using related array data (GSE54129, GSE29272) from the GEO database." (PMID 35368661, 2022). "Previous studies have concluded that GGT5 overexpression is correlated with a poor prognosis in patients with lung cancer, gastric cancer, and colon cancer." (PMID 35368661, 2022). "First, we compared the differential expression of GGT5 between gastric cancer tissues and normal gastric mucosa in the cancer genome atlas (TCGA) and GEO NCBI databases using the most widely available data." (PMID 35368661, 2022).
gastric cancer (continued). "There was a large degree of heterogeneity across cancers, and only a few of the tumor types, including gastric cancer, had high GGT5 expression levels." (PMID 35368661, 2022). "To evaluate the prognostic value of GGT5 in gastric cancer, we calculated the survival of patients with different GGT5 expression levels using the Kaplan-Meier method." (PMID 35368661, 2022). "All of the results indicated that GGT5 expression levels were elevated in gastric cancer tissues compared with normal tissues (p < 0.05)." (PMID 35368661, 2022). "In short, we concluded that there is an elevated expression level of GGT5 in gastric cancer tissues, which was related to advanced tumor stage and poor prevision." (PMID 35257007, 2022). "The ROC curve was plotted to determine the sensitivity and specificity of GGT5 to distinguish gastric cancer tissues from normal gastric mucosa." (PMID 35368661, 2022). "WB results showed that the expression of GGT5 in gastric cancer tissues was significantly higher than that in normal tissues." (PMID 35257007, 2022). "Based on the TIDE algorithm to test the clinical response to immune checkpoint blockade, we demonstrated a significantly lower predicted response rate of gastric cancer patients in the GGT5-high expression group." (PMID 35368661, 2022). "In addition, GGT5 is considered a key metabolism‐related gene in gastric cancer, colon cancer, ovarian cancer, and B‐cell lymphoma and is associated with tumor progression and poor prognosis." (PMID 41316810, 2025). "Furthermore, the clinical correlation analysis revealed that GGT5 expression is elevated in higher grades of gastric cancer, such as histologic grade 3 and T stages III-IV." (PMID 38748299, 2024). "Nonetheless, the role of GGT5 in gastric cancer and its specific mechanisms remain unexplored." (PMID 38581025, 2024). "A deeper comprehension of the role of GGT5 in these pathways may offer valuable insights for the treatment of gastric cancer." (PMID 38748299, 2024). "The prognostic significance of GGT5 expression levels in gastric cancer patients was also explored." (PMID 38581025, 2024). "Moreover, higher GGT5 expression in gastric cancer is correlated with poor clinical outcomes based on OS, DFI, PFI, and DSS analyses." (PMID 38748299, 2024). "Furthermore, our investigation indicated higher GGT5 expression in gastric cancer cell lines compared to normal mucosal cell lines (p < 0.01)." (PMID 38581025, 2024). "Finally, gene ontology annotation, Kyoto Encyclopedia of Genes and Genomes (KEGG), and Gene Set Enrichment Analysis (GSEA) were applied to explore the potential functions of GGT5 in gastric cancer." (PMID 35368661, 2022). "To define the clinical correlation between the GGT5 expression level and the clinicopathological features in gastric cancer, we further analyzed the differences in clinical characteristics between the GGT5-high and GGT5-low expression groups based on the TCGA database." (PMID 35368661, 2022). "Moreover, gastric cancer patients with high GGT5 expression showed worse 10-years overall survival (p = 0.008) and progression-free intervals (p = 0.006) than those with low GGT5 expression." (PMID 35368661, 2022). "GSEA was performed to ascertain the related signaling pathways of GGT5 in gastric cancer." (PMID 35368661, 2022). "Taken together, we confirmed that GGT5 was highly expressed in gastric cancer tissues compared to normal samples, and it could be identified as a specific biomarker for distinguishing gastric cancer tissues from normal gastric mucosa." (PMID 35368661, 2022). "Our present study has confirmed that GGT5 plays a critical role in the progression of gastric cancer and could serve as an independent prognostic factor for gastric cancer patients." (PMID 35368661, 2022). "The results showed that the area under the ROC curve was 0.754, which indicated that GGT5 might potentially contribute to the identification of gastric cancer tissues." (PMID 35368661, 2022).
gastric cancer (continued). "The results showed that GGT5 was upregulated in gastric cancer tissues compared to normal tissues." (PMID 35368661, 2022). "Based on the enrichment analyses, we may infer that GGT5 plays important role in promoting the carcinogenesis and development of gastric cancer via a series of biological processes, such as immune response, angiogenesis, and inflammatory response." (PMID 35368661, 2022). "Furthermore, the protein level of GGT5 was also found to be higher in gastric cancer tissue than that in normal tissues in the HPA database." (PMID 35368661, 2022). "Therefore, it is necessary to conduct further experiments to investigate the detailed mechanism of GGT5 in gastric cancer." (PMID 35257007, 2022). "GGT5 was also regarded as the key metabolism-related gene in gastric cancer and colon cancer." (PMID 34513707, 2021). "To further investigate GGT5 expression in gastric cancer, we utilized Western blotting (WB) and immunohistochemistry (IHC) to evaluate GGT5 protein levels in gastric cancer cell lines and 90 cases of gastric cancer along with their corresponding adjacent normal tissue samples." (PMID 38581025, 2024). "As GGT5 is a protein-coding gene, to validate the predictive results, we also analyzed the IHC staining results, revealing significantly lower overall survival (OS) among gastric cancer patients with high GGT5 expression protein compared to those with low expression (p = 0.046)." (PMID 38581025, 2024). "Associations between GGT5 protein expression and clinicopathological parameters (age, gender, tumor location, tumor size, histological differentiation, neural/vascular invasion, lymph node metastasis, and TNM stage) in patients with gastric cancer were explored." (PMID 38581025, 2024). "Taken together, GGT5 is an immune-related gene and may play a critical role in inflammatory responses, angiogenesis, and the tumor immune response to promote the development and progression of gastric cancer." (PMID 35368661, 2022). "This study shows that GGT5 serves as an active gene of GSH metabolism and promotes progression, drug resistance, and immune microenvironmental remodeling in gastric cancer." (PMID 38748299, 2024). "Nevertheless, GGT5’s role in gastric cancer (GC) remains ambiguous." (PMID 38581025, 2024). "Moreover, the interplay between GGT5 and memory CD8+ T cells and their influence on gastric cancer has rarely been studied." (PMID 38748299, 2024). "Third, the expression level of GGT5 in each stage of gastric cancer was not provided in detail in our study." (PMID 38581025, 2024). "The immune checkpoint analysis indicated that gastric cancer patients with upregulated GGT5 expression showed a higher TIDE score and expression of CD274, CTLA4, HAVCR2, LAG3, PDCD1, PDCD1LG2, and TIGIT than patients in the GGT5-low expression group." (PMID 35368661, 2022). "However, the correlation of GGT5 expression levels with immune cell infiltration in the tumor microenvironment of gastric cancer has not yet been investigated yet." (PMID 35368661, 2022).